SIRT3 (sirtuin 3)
Diseases named in the same sentence as SIRT3 in open-access papers (continued):
Sharing a sentence is not in itself a finding about the gene and the disease.
kidney (11 papers, 2017 to 2025). "In both folic acid- and IRI induced-AKI models, increased SUMO1 conjugation to Sirt3 was observed, and SENP1-mediated deSUMOylation of Sirt3 alleviated kidney injury." (PMID 41350286, 2025). "Previous studies have confirmed the role of SIRT3 as a protectant against acute kidney tissue injury." (PMID 38270316, 2024). "We conclude that exosomal miR-195a-5p mediate the communication between autophagy-deficient Mφ and TECs, leading to impaired mitochondrial biogenetic in TECs and subsequent exacerbation of kidney injury in AKI mice via miR-195a-5p-SIRT3 axis." (PMID 38782909, 2024). "The findings of the present research indicate that DEX may lessen liver IR damage via altering SIRT3’s expression in mitochondrial quality control." (PMID 39955447, 2025).
neurological diseases (6 papers, 2019 to 2025). "SIRT3 may also mediate the remission of physical exercise in neurological disorders caused by severe metabolic diseases." (PMID 36374406, 2023). "Therefore, deacetylation of CypD by the compensatory activation of SIRT3 under CR conditions inhibits mitochondrial permeability, thereby promoting mitochondrial calcium retention, which in turn inhibits neurological diseases caused by excitotoxic substances and calcium overload." (PMID 36374406, 2023). "Based on existing evidence, SIRT3 emerges as a promising therapeutic target, offering novel strategies for treating neurological diseases." (PMID 40969935, 2025). "In summary, GABAergic neurons not only ameliorate neurological disorders through interactions with SIRT3 but also exhibit complex interplay with glutamatergic neurons." (PMID 40969935, 2025). "Increasing evidence has shown that SIRT3 plays significant physiological and pathological roles in neurological disorders." (PMID 39091611, 2024). "In most cases, SIRT3 can inhibit clinical manifestations of neurological diseases by promoting autophagy, energy production, and stabilization of mitochondrial dynamics, and by inhibiting neuroinflammation, apoptosis, and oxidative stress (OS)." (PMID 36374406, 2023). "This review comprehensively summarizes the different roles and related mechanisms of SIRT3 in neurological diseases." (PMID 36374406, 2023). "This is expected to provide theoretical support for future research on the relationship between rehabilitation training, SIRT3, and neurological diseases." (PMID 36374406, 2023). "As a deacetylase, SIRT3 actively regulates the occurrence and development of neurological diseases through the regulation of downstream proteins." (PMID 36374406, 2023). "Considerable evidence has shown that the content and activity of SIRT3 are altered in neurological diseases." (PMID 36374406, 2023). "SIRT3 has gradually become a potential therapeutic target for the treatment of metabolic and neurological diseases." (PMID 35084580, 2022). "Sirt3 is one of the sirtuin family members, which plays an important role in the development of neurological diseases." (PMID 31729962, 2019). "Sirt3 belongs to the sirtuin protein family, which plays an important role in the development of neurological diseases." (PMID 31729962, 2019). "Based on the complex relationship between glutamate and SIRT3, further exploration of strategies to balance their expression may provide novel therapeutic directions for neurological diseases." (PMID 40969935, 2025). "Therefore, in this review, we summarize the different roles and related mechanisms of SIRT3 in neurological diseases and summarize several rehabilitation training methods related to SIRT3 that can improve the prognosis of neurological diseases." (PMID 36374406, 2023). "This suggests that the beneficial effects of exercise on neurological diseases may be related to the anti-OS effect of SIRT3." (PMID 36374406, 2023). "Moreover, to provide more ideas for the prognosis of neurological diseases, we summarize several SIRT3-mediated rehabilitation training methods." (PMID 36374406, 2023). "SIRT3 mainly inhibits various types of neurological diseases." (PMID 36374406, 2023). "Furthermore, SIRT3 affects the occurrence and development of neurological diseases." (PMID 36374406, 2023). "However, only one report has pointed to the deleterious effects of SIRT3 in nonneoplastic neurological diseases." (PMID 36374406, 2023). "In addition, the negative effects of SIRT3 on neurological diseases are mainly manifested in tumors because SIRT3 is ultimately responsible for the survival of nervous system cells through various forms of regulation." (PMID 36374406, 2023). "In addition, although the subjects in some studies did not have neurological diseases, exercise and CR were shown to inhibit OS, inhibit inflammation, and promote autophagy through SIRT3." (PMID 36374406, 2023).
inflammation (5 papers, 2020 to 2025). Aberrant reaction of the microcirculation characterized by movement of fluid and leukocytes from the blood into extravascular tissues. "Taken together, these results indicated that Sirt3 deficiency led to increased Ang II-induced vascular inflammation, overexpression of MMPs, increased ROS production, and HASMC apoptosis in vitro." (PMID 34095262, 2021). "Furthermore, we showed that the VE-cadherin/β-catenin complex dissociated upon lung inflammation, while Sirt3 promoted the stability of such a complex." (PMID 34630854, 2021).
mitochondrial disease (4 papers, 2022 to 2025). "This combination (CoC3) activates SIRT3 and mtUPR, as well as enhance sirtuin levels and mitochondrial biogenesis and activity in several cell models of mitochondrial diseases." (PMID 40563372, 2025). "In summary, pterostilbene in combination with mitochondrial cofactors treatment activates SIRT3 and UPRmt as compensatory mechanisms as well as enhance sirtuins’ levels and mitochondrial activity in several cell models of mitochondrial diseases." (PMID 35370630, 2022). "However, the reverse was seen in the PD and mitochondrial disease cases (effect size<0.25), showing a significant loss of response compared to the controls (ANOVA, p = 0.035, PD, p = 0.041, MITO, SIRT3; PD, p = 0.006, MITO, p = 0.008, PINK1)." (PMID 37553379, 2023). "Therefore, we suggest that SIRT3 and mtUPR could be two potential therapeutic targets for the treatment of mitochondrial diseases, as we have observed in this study." (PMID 38786005, 2024).
bacterial infection (3 papers, 2021 to 2025). "Our current study is the first to identify a potential role of the PGC-1α-SIRT3 axis in the regulation of the inflammasome response in bacterial infection." (PMID 35215060, 2022). "It is also the first to investigate the novel small molecule, ZLN005, in a model of bacterial infection and the first to investigate its role in the activation of SIRT3." (PMID 35215060, 2022).
brain disorder (2 papers, 2014 to 2024). A disease affecting the brain or part of the brain. "SIRT3 has been shown to be highly correlated with disease severity and prognosis in brain disorders, and animal studies have also indicated that overexpression of SIRT3 could alleviate pathological damage in epileptic rats." (PMID 39091611, 2024). "Thus, metabolic rescue observed upon overexpression of Sirt3 may represent an appropriate strategy to avoid neuronal death in a broad range of oxidative stress related brain disorders." (PMID 25196599, 2014).
genetic diseases (2 papers, 2017). "Starting with energy homeostasis and metabolism, SIRT3 impacts nuclear and muscular function, reduces the effects of aging, and mediates several genetic diseases." (PMID 27686535, 2017). "Moreover, SIRT3/4/5 exists in mitochondria as deacetylase that function as metabolism regulators, which suggests their relevance of the treatment of inherited diseases related to mitochondrial metabolism." (PMID 27659520, 2017).
infectious disease (2 papers, 2024 to 2025). A disorder directly resulting from the presence and activity of a microbial, viral, or parasitic agent in humans. "In our study, knockout and overexpression of differential SIRT3 proteins are significantly enriched in the viral protein interaction with cytokine and cytokine receptor pathways, and their application in infectious diseases needs to be evaluated with caution." (PMID 40943150, 2025).
blood cancer (1 paper, 2020). "We previous found that in a non‐aging blood cancer cell line, Sirt3 appears to be associated with elevated oxidative stress and is downregulated by autophagy." (PMID 32951306, 2020).
bone disorder (1 paper, 2025). "However, it is still unclear whether and how SIRT3 drives IR exposure-induced bone disorders." (PMID 40584154, 2025).
CNS disorders (1 paper, 2025). "Therefore, it is imperative to conduct more in-depth and extensive investigations into the mechanisms underlying SIRT3 in central nervous system disorders." (PMID 40969935, 2025). "It further analyzed the potential pharmacological mechanisms of several SIRT3 agonists and explored their therapeutic value in improving CNS disorders." (PMID 40969935, 2025).
head and neck tumors (1 paper, 2016). "Statistical significant decrease in SIRT3 expression was observed in relation to T-stage (p<0.003), N-stage (p<0.01) and M-stage (p<0.04) of the head and neck tumors." (PMID 26785117, 2016).
heart (1 paper, 2024). "Previous studies have demonstrated that SIRT3 acts as a protective factor against ischemic heart injury, and might prevent myocardial injury by targeting mitochondrial dysfunction." (PMID 39872885, 2024).
hematological diseases (1 paper, 2022). "In an in silico approach, we conducted an analysis in the GEPIA database, and we validated the results of the present systematic review when we observed that the SIRT1, SIRT3, SIRT5 and SIRT6 genes are also up-regulated in onco-hematological diseases such as DBLC when compared with normal tissues." (PMID 36230534, 2022).
movement disorder (1 paper, 2017). Neurological conditions resulting in abnormal voluntary or involuntary movement, which may impact the speed, fluency, quality and ease of movement. "Based on these previous findings, we aimed to study the mitochondrial respiration in intact PBMCs in relation to the expression and activity of SIRT3 in patients with movement disorders." (PMID 29081897, 2017). "The aim of the study was to analyze the mitochondrial respiration in peripheral blood mononuclear cells (PBMCs) and the SIRT3 activity in patients with movement disorders." (PMID 29081897, 2017). "This may indicate that SIRT3 is also involved in the protection of the mitochondrial respiration in patients with movement disorders." (PMID 29081897, 2017). "We have not found correlation between SIRT3 activity or SIRT3 expression and duration of movement disorders." (PMID 29081897, 2017). "SIRT3 activity, but not SIRT3 protein content in PBMCs, was significantly reduced in our cohort of patients with movement disorders and particularly those with PD." (PMID 29081897, 2017). "We have not found differences in the expression of SIRT3 protein in PBMCs from patients with movement disorders and controls; however, the deacetylase activity was significantly lower in patients with movement disorders." (PMID 29081897, 2017). "In movement disorders without α-syn pathology (n = 9, PSP and CDB), we have found a positive correlation (r = 0.714; P = 0.0465) between ROUTINE respiration and SIRT3 expression in PBMCs and positive correlation between ROX and SIRT3 expression in PBMCs (r = 0.833; P = 0.0102)." (PMID 29081897, 2017).
SIRT3 also shares sentences with these, for which no sentence is quoted: hypertrophy (9 papers); pulmonary hypertension (7); Glucose intolerance (5); acute myocardial infarction (3); cognitive disorder (3); Klebsiella pneumoniae pneumonia (3); acute respiratory distress syndrome (2); brain infarct (2); cerebral artery occlusion (2); essential hypertension (2); oral diseases (2); osteonecrosis (2); pancreatic ductal adenocarcinoma (2); septic shock (2); acute lymphoblastic leukemia (1); advanced heart failure (1); albuminuria (1); alcoholic cirrhosis (1); anemia (1); anxiety-like behavior (1); autism (1); bacterial pneumonia (1); bone metabolism disorders (1); brain edema (1); breast adenocarcinoma (1); cerebral infarction (1); diabetic encephalopathy (1); diabetic foot ulcer (1); dyslipidaemia (1); Encephalopathy (1).
A further 46 diseases each share a sentence with SIRT3 in 1 paper.